SHMT2 (serine hydroxymethyltransferase 2)
Diseases named in the same sentence as SHMT2 in open-access papers (continued):
Sharing a sentence is not in itself a finding about the gene and the disease.
diffuse large B-cell lymphoma (4 papers, 2020 to 2025). "Selective SHMT2 inhibitors could be useful for the treatment of malignancies like diffuse large B-cell lymphoma where glycine uptake is impaired and cancer cells are solemnly depending on mitochondrial 1C metabolism for glycine production." (PMID 33707653, 2021). "Low-molecular-weight SHMT2 inhibitors SHIN1 and SHIN2 have been developed and shown to have anti-cancer activities against large diffuse B-cell lymphoma opening the way toward experimental evaluation of SHMT2 as a drug target in PPGL." (PMID 37749499, 2023).
head and neck cancer (4 papers, 2022 to 2025). A primary or metastatic malignant neoplasm affecting the head and neck. "SHMT2 induces stemness of head and neck cancer, Burkitt lymphoma." (PMID 40097394, 2025). "SHMT2 was aberrantly highly expressed in head and neck cancer." (PMID 37932821, 2023). "However, the function and mechanism of SHMT2 in head and neck cancer (HNC) are not clear." (PMID 36077112, 2022).
leukemia (4 papers, 2021 to 2023). A malignant (clonal) hematologic disorder, involving hematopoietic stem cells and characterized by the presence of primitive or atypical myeloid or lymphoid cells in the bone marrow and the blood. "Loss of both SHMT1 and SHMT2 was necessary for impaired growth and cell cycle arrest, with suppression of both SHMT1 and SHMT2 inhibiting leukemia progression in vivo." (PMID 34341479, 2022). "Redundancy of SHMT1 and SHMT2 enzymes has been shown in HEK293T and HCT-116 cells, though it is unclear if this occurs in leukemia." (PMID 34341479, 2022).
pancreatic cancer (4 papers, 2018 to 2025). "Compared with SHMT2, the biological role of SHMT1 in pancreatic cancer remains poorly understood." (PMID 40738465, 2025). "Although the L474F site of SHMT1 was not confirmed to have a direct protective effect against pancreatic cancer, the study suggested that the loss of SHMT1 nuclear localization may be compensated by SHMT2 through metabolic mechanisms, thereby playing a role in the tumor environment." (PMID 40738465, 2025). "As such, one might predict that expression of this SNP would confer a protective effect against development of pancreatic cancer; however, expression of a cytoplasmic isozyme of SHMT2, SHMT2α, appears to functionally compensate for lack of wild-type SHMT1 protein." (PMID 29474406, 2018).
renal carcinoma (4 papers, 2021 to 2025). A carcinoma arising from the epithelium of the renal parenchyma or the renal pelvis. "SHMT2, a key enzyme in one-carbon metabolism, may be associated with the immunotherapy response in patients with renal cancer." (PMID 40332099, 2025). "Our findings suggested that SHMT2 may be associated with the immunotherapy response in patients with renal cancer; therefore, SHMT2 may be a potential novel target for combination immunotherapy." (PMID 36110969, 2022). "Targeting PDK1 and SHMT2 lactylation may inhibit glycolysis and reduce tumor progression in renal cancer." (PMID 41458606, 2025).
tongue squamous cell carcinoma (4 papers, 2021 to 2023). A squamous cell carcinoma that arises from the tongue. "The top hit with an adjusted P-value of 3.82 × 10−11 was the ‘Cell cycle’, and a previous study showed that silencing SHMT2 inhibits the progression of tongue squamous cell carcinoma through cell cycle regulation." (PMID 36525367, 2023). "The depletion of SHMT2 could suppress the progression of tongue squamous cell carcinoma by mediating the cell cycle." (PMID 36213384, 2022). "Additionally, other researchers found that knocking down SHMT2 inhibited cancer progression by inducing the prolongation of the G1 phase of the cell cycle in tongue squamous cell carcinoma." (PMID 36077112, 2022).
anemia (3 papers, 2019 to 2025). A reduction in the number of red blood cells, the amount of hemoglobin, and/or the volume of packed red blood cells. "Disruption of the Shmt2 gene in murine models has been shown to cause embryonic anemia due to impaired mitochondrial OCM, highlighting the essential function of this enzyme in cellular energy homeostasis." (PMID 40738465, 2025). "It has been reported that the Shmt2 gene deletion in mice causes mitochondrial respiratory dysfunction, leading to growth retardation, embryonic lethality, and anemia by Embryonic Day 13.5 (E13.5)." (PMID 39456851, 2024). "We speculate that the reduced fetal liver size is attributable to anemia from blocked red blood cell development due to Shmt2 deficiency, thereby impacting liver development." (PMID 39456851, 2024). "A previous study reported that disruption of Shmt2 in mice resulted in embryonic anemia due to impaired erythropoiesis, indicating a SHMT2 critical role in early development." (PMID 40738465, 2025). "Detailed progression analysis of anemia revealed that Shmt2 deletion exerts stage-specific effects on the development and maturation of erythroid cells." (PMID 39456851, 2024). "In conclusion, our findings suggest that the specific deletion of Shmt2 in the hematopoietic system leads to prominent anemia-like symptoms in adult mice, likely due to the defect of erythroid development and impaired enucleation processes." (PMID 39456851, 2024). "In this study, to explore the hematopoietic system abnormalities and anemia phenotypes arising from the conditional knockout of Shmt2, we utilized the Cre-lox recombination system to establish the Vav1-Cre/Shmt2fl/fl embryonic and adult mouse model." (PMID 39456851, 2024). "Our findings demonstrated that the deletion of Shmt2 within the hematopoietic system led to the distinctive anemia phenotype in both fetal and adult mice." (PMID 39456851, 2024). "This assertion is supported by evidence that the disruption of mouse Shmt2 induces mitochondrial respiration defects in mouse embryonic fibroblasts generated from Shmt2-knockout E13.5 embryos experiencing anaemia and lethality." (PMID 31690790, 2019). "This study elucidated the potential mechanisms by which the disruption of Shmt2 induces embryonic anaemia in Shmt2-knockout mouse embryos." (PMID 31690790, 2019). "By contrast, mitochondrial respiration defects in foetal livers also induced depletion of erythroblasts as a consequence of the inhibition of erythroblast differentiation, resulting in the manifestation of anaemia in Shmt2-knockout E13.5 embryos." (PMID 31690790, 2019). "Here, we elucidated the potential mechanisms by which the disruption of this gene induces mitochondrial respiration defects and embryonic anaemia using Shmt2-knockout E13.5 embryos." (PMID 31690790, 2019). "Interestingly, we observed that, while anemia symptoms manifested in conditional Shmt2 knockout mice as early as E13.5, these mice were still born and able to survive." (PMID 39456851, 2024). "Subsequent analyses indicated that the specific deletion of Shmt2 in the hematopoietic system leads to a significant anemia phenotype in the peripheral blood of adult mice, which may be caused by immature erythroid development." (PMID 39456851, 2024). "Given this role, we hypothesize that SHMT2 is crucial for erythroid differentiation and anemia pathogenesis, although few studies have addressed this." (PMID 39456851, 2024). "However, Shmt2-knockout embryos eventually show lethality resulting from the second crisis (i.e., the manifestation of anaemia)." (PMID 31690790, 2019). "The observed reduction in fetal liver size is likely attributable to impaired erythroid development resulting from SHMT2 deficiency, which in turn could lead to anemia and compromise normal fetal liver development without inducing embryonic lethality." (PMID 39456851, 2024).
anemia (continued). "Here, we studied the livers and brains of Shmt2-knockout E13.5 embryos to identify the potential mechanisms by which Shmt2 disruption induces mitochondrial respiration defects and growth retardation preferentially in foetal livers and confers anaemia in Shmt2-knockout E13.5 embryos." (PMID 31690790, 2019). "Therefore, not only growth retardation but also mitochondrial respiration defects and the resulting arrest of erythroblast differentiation induced erythroblast depletion in foetal livers and were responsible for the manifestation of anaemia in Shmt2-knockout embryos." (PMID 31690790, 2019). "This study identified potential mechanisms by which Shmt2 disruption induces mitochondrial respiration defects and growth retardation and the manner in which these abnormalities are preferentially manifested in the livers of Shmt2-knockout E13.5 embryos and induce anaemia." (PMID 31690790, 2019). "Therefore, while growth retardation in foetal livers induces the depletion of erythroblasts, mitochondrial respiration defects also induce the depletion of erythroblasts via inhibition of erythroblast differentiation and division, resulting in the manifestation of anaemia in Shmt2-knockout embryos." (PMID 31690790, 2019).
Burkitt lymphoma (3 papers, 2022 to 2025). A rare form of malignant mature B-cell non-Hodgkin lymphoma. "In Burkitt lymphoma, SHMT2 expression correlated significantly with the effect of immunotherapy." (PMID 36110969, 2022).
cardiomyopathy (3 papers, 2023 to 2025). A disease of the heart muscle or myocardium proper. "Mutations in SHMT2 result in neurodevelopmental disorders with cardiomyopathy, spasticity, and brain abnormalities (NEDCASB)." (PMID 38822427, 2024). "Related to glycine and folate metabolism, deficiencies in the expression level or activity of the SHMT2 enzyme led to decreased glycine levels, loss of mitochondrial homeostasis and folate deficiency, which together lead to microcephaly, intellectual disability, and cardiomyopathies." (PMID 40076950, 2025).
clear cell renal cell carcinoma (3 papers, 2020 to 2024). "After data mining by multiple bioinformatic tools, these results suggested that NDUFA4L2 was also high expressed in various types of kidney cancer and was associated with worse OS in patients with renal clear cell carcinoma, like SHMT2." (PMID 33066813, 2020). "We found that overexpressed SHMT2 is associated with worse overall survival (OS) patients with renal clear cell carcinoma, with P = 0.033 and HR = 1.41 (1.03–1.94)." (PMID 33066813, 2020). "However, the expression, function, and underlying mechanisms of SHMT2 in clear cell renal cell carcinoma (ccRCC) remain largely unknown." (PMID 36806313, 2023). "Like SHMT2, overexpressed NDUFA4L2 also was associated with worse OS in patients with renal clear cell carcinoma and renal papillary cell carcinoma (P < 0.05, respectively)." (PMID 33066813, 2020). "We explored the expression of SHMT2 in normal and renal clear cell carcinoma tissues based on clinicopathologic parameters, such as cancer stage, age, race, and tumor grade by using UALCAN database." (PMID 33066813, 2020). "As a protein coding gene, SHMT2 also possessed prognostic value for renal clear cell carcinoma, which was also validated by immunohistochemical staining from pathological tissues and healthy tissues." (PMID 33066813, 2020). "In clear cell renal cell carcinoma, siRNA knockdown of SHMT2 expression disrupted mitochondrial structure and function, reduced one-carbon metabolism, overactivated the autophagy-lysosomal pathway, resulting in an increase in LMP, and ultimately led to apoptosis." (PMID 38594513, 2024). "In addition, we also confirmed that mRNA expression levels of SHMT2 was significantly increased in renal clear cell carcinoma tissues than in normal renal tissues, which further verified the results from GEPIA database." (PMID 33066813, 2020). "Moreover, we also analyzed the correlation of SHMT2 expression with clinicopathological features from patients with renal clear cell carcinoma." (PMID 33066813, 2020). "Moreover, high expression of SHMT2 and NDUFA4L2 predicted poor OS in patients with renal clear cell carcinoma." (PMID 33066813, 2020). "SHMT2 was up-regulated in 7 various kidney cancer datasets, compared to normol tissues (P‐value < 0.05 and Fold change > 2) including Renal Wilms Tumor, Clear Cell Renal Cell Carcinoma, Non-Hereditary Clear Cell Renal Cell Carcinoma and Hereditary Clear Cell Renal Cell Carcinoma." (PMID 33066813, 2020).
kidney cancer (3 papers, 2020 to 2023). Primary or metastatic malignant neoplasm involving the kidney. "High SHMT2 expression is associated with poor overall survival in patients with kidney cancer." (PMID 33066813, 2020). "Only one study based on statistical analysis of a database pointed out the clinical significance of SHMT2 in kidney cancer and provided a potential therapeutic target." (PMID 36806313, 2023). "The comparisons of mRNA levels of SHMT2 in kidney cancer and healthy samples in each individual dataset were performed by using the Student’s t-test." (PMID 33066813, 2020). "Our studies investigated the expression of SHMT2 in kidney cancer by Oncomine, Human Protein Atlas database and ULCAN database." (PMID 33066813, 2020). "Then Analysis of SHMT2’s co-expressed genes in kidney cancer discovered that NDUFA4L2 was the primary co-expressed gene with SHMT2 in kidney cancer." (PMID 33066813, 2020). "Using the Kaplan–Meier plotter, the prognostic values of SHMT2 in various kidney cancers were predicted." (PMID 33066813, 2020). "Utilizing the Oncomine database, we discovered the expression levels of SHMT2 in different kinds of kidney cancer with those in control samples." (PMID 33066813, 2020). "After experimental validation, we hoped that the assessment of both SHMT2 and its co-expressed gene in kidney cancer will be helpful in predicting kidney cancer prognosis and providing a novelty therapeutic target for individual treatment of kidney cancer." (PMID 33066813, 2020). "The IHC pictures validated that the SHMT2 showed a strongly intensity in kidney cancers compared with those in healthy samples." (PMID 33066813, 2020). "In our studies, we tried to explore the expression and prognosis of SHMT2 and its co-expression gene in kidney cancer for the first time by using multiple bioinformatics database." (PMID 33066813, 2020). "And a recent publication also showed that SHMT2 is overexpressed in kidney cancers, particulay in the high stage tumors." (PMID 33066813, 2020). "In current research, we found that SHMT2 is overexpressed in different kinds of kidney cancer with those in control samples." (PMID 33066813, 2020). "Like SHMT2, overexpressed NDUFA4L2 also was associated with worse overall survival in patients with kidney cancer." (PMID 33066813, 2020). "Only one study pointed out the clinical significance of SHMT2 in kidney cancer, but the underlying mechanism was not investigated." (PMID 36806313, 2023). "The present study might be benefit for better understanding the clinical significance of SHMT2 and provided a potential therapeutic target for kidney cancer in future." (PMID 33066813, 2020). "SHMT2 was found to be increased in 7 kidney cancer datasets, compared to normal renal tissues." (PMID 33066813, 2020). "The present study might be benefit for better understanding the clinical significance of SHMT2 and provided a potential therapeutic target for kidney cancer research in the future." (PMID 33066813, 2020). "Our investigations may helpful to further fill in the blank and understand the biological significance of SHMT2 in kidney cancer." (PMID 33066813, 2020). "Through co-expression analysis by cBioPortal database, we identified a SHMT2’s co-expressed gene, NDUFA4L2, in kidney cancer." (PMID 33066813, 2020). "In summary, SHMT2 and its co-expressed gene NDUFA4L2 were significantly overexpressed in various kinds of kidney cancer." (PMID 33066813, 2020). "Based on above results, overexpressed SHMT2 and its co-expressed gene NDUFA4L2 were all correlated with the prognosis in kidney cancer." (PMID 33066813, 2020). "And its expression profile and clinical significance of SHMT2 in human kidney cancer have not yet been investigated." (PMID 33066813, 2020). "Second, the upstream molecule on the roles of SHMT2 in kidney cancer lack of further exploration." (PMID 33066813, 2020). "However, current studies have not focused on the relationship between SHMT2 and kidney cancer." (PMID 33066813, 2020).
kidney cancer (continued). "Unlike SHMT2, NDUFA4L2 had been reported to be involved in the occurrence and development of kidney cancer." (PMID 33066813, 2020).
osteoarthritis (3 papers, 2015 to 2021). A noninflammatory degenerative joint disease occurring chiefly in older persons, characterized by degeneration of the articular cartilage, hypertrophy of bone at the margins and changes in the synovial membrane. "miR‐370 and miR‐373 regulate the pathogenesis of osteoarthritis by modulating one‐carbon metabolism via SHMT‐2 and MECP‐2, respectively." (PMID 31808597, 2020).